LDHB (lactate dehydrogenase B)
Diseases named in the same sentence as LDHB in open-access papers (continued):
Sharing a sentence is not in itself a finding about the gene and the disease.
osteosarcoma (7 papers, 2019 to 2025). A usually aggressive malignant bone-forming mesenchymal neoplasm, predominantly affecting adolescents and young adults. "In osteosarcoma cell lines, LDHB was found to be highly expressed with an elevated mRNA levels in tissues with metastasis; advanced stages and recurrence and was overall associated with a poor prognosis in osteosarcoma patients." (PMID 31146503, 2019). "Furthermore, the correlation between the overexpression of LDHB and the growth, proliferation, migration, and invasion of osteosarcoma cell lines has been identified." (PMID 36551514, 2022). "High expression of LDHB was also identified in osteosarcoma." (PMID 36551514, 2022). "Therefore, increased LDHB expression in patients with osteosarcoma might be a significant prognostic marker for tumor recurrence and poor overall survival." (PMID 36551514, 2022).
glioblastoma (6 papers, 2016 to 2025). The most malignant astrocytic tumor (WHO grade IV). "LDHB expression is associated with poor survival in many human cancers, and the pivotal role of pyruvate–lactate interconversion bears translational implications, as recently demonstrated in glioblastoma (GBM)." (PMID 37895048, 2023). "Indeed, it was recently shown that the combined deletion of LDHA and LDHB in human glioblastoma xenografts prolongs survival after RT60." (PMID 40090955, 2025). "Excitingly, a natural micropeptide that localizes to mitochondria where it interacts with LDHA and LDHB to prevent the conversion of lactate to pyruvate was also recently identified and shown to inhibit the growth and tumorigenicity of patient-derived primary glioblastoma cells." (PMID 40090955, 2025). "The authors demonstrated that in glioblastoma tissue, LDHA and LDHB are spatially differentially expressed and only a few cells expressed both isoforms." (PMID 36852624, 2023). "We performed the dual reporter assay in HeLa cells and two glioblastoma cell lines, U118 and U373, and compared MDH1 and LDHB readthrough." (PMID 27881739, 2016). "When analysing the LDHB SCC in HeLa, HEK, COS-7 and U118 cells using our reporter assay, readthrough was found to be highest in the glioblastoma cell line U118." (PMID 27881739, 2016).
cardiac hypertrophy (5 papers, 2021 to 2025). "In cardiomyocytes, miR-375 inhibitors inhibited Ang II-induced myocardial hypertrophy by promoting lactate dehydrogenase B (LDHB) expression." (PMID 36748222, 2023). "MiR-375-3p was recently found to promote cardiac hypertrophy by reducing protein expression of lactate dehydrogenase B chain, a regulator of cell metabolism." (PMID 34925023, 2021). "A recent study identified a correlation between LDHB and cardiac hypertrophy and suggested a molecular mechanism for regulating abnormal energy metabolism in cardiac hypertrophy." (PMID 33996940, 2021). "LDHB may be an appropriate target to improve abnormal cardiac energy metabolism in the setting of cardiac hypertrophy." (PMID 33996940, 2021). "In our current study, less pronounced cardiac hypertrophy signs demonstrated in animals fed the 5:1 diet, which was characterized by a higher n-3 PUFA content, led to the assumption that this effect was due to the increased myocardial LDHB expression." (PMID 33498641, 2021). "Sildenafil treatment in vivo or administration of cGMP and Sildenafil, in vitro, induces an increase in the expression and activity of oxidative LDHB in Pde5a+/+ 27G TAC mice, that, however, is not sufficient to revert cardiac hypertrophy." (PMID 40659490, 2025).
medulloblastoma (5 papers, 2019 to 2023). A malignant, invasive embryonal neoplasm arising from the cerebellum. "It has been proven that the expression of LDHB alone was not able to predict a difference in OS, but the concomitant expression of LDHB and CCNB1 was able to identify medulloblastoma patients with a significantly worse prognosis." (PMID 33553434, 2021).
Immunodeficiency (4 papers, 2022 to 2025). Failure of the immune system to protect the body adequately from infection, due to the absence or insufficiency of some component process or substance. "In the process of GSEA results of the four diagnostic genes (APRT, ARG1, UMPS, and LDHB) suggested that these four diagnostic genes were mainly enriched in mitochondrial gene expression, primary immune deficiency, other energy metabolism-related functions, and immune-related pathways." (PMID 40774030, 2025).
myocardial infarction (4 papers, 2011 to 2022). Gross necrosis of the myocardium, as a result of interruption of the blood supply to the area, as in coronary thrombosis. "LDHB is one of the important enzymes of glycolysis and gluconeogenesis, typically used to monitor myocardial infarction." (PMID 35978348, 2022). "Since LDHB is generally used as an index for myocardial infarction, we chose LDHB as the candidate protein to verify the data of 2-DE gels." (PMID 21915278, 2011). "These proteins included several important blood biomarkers like the indicators for myocardial infarction LDHA/LDHB, the coagulation factor F7, the liver injury marker CPS1, the infection marker CRP, the metabolic syndrome marker FABP534 and the inflammatory predictor GSN35." (PMID 34373457, 2021). "The expression level of LDHB increases in response to myocardial infarction." (PMID 31993089, 2020).
non-small cell lung carcinoma (4 papers, 2011 to 2024). A group of at least three distinct histological types of lung cancer, including non-small cell squamous cell carcinoma, adenocarcinoma, and large cell carcinoma. "The expression of LDHB was elevated in primary non-small cell lung cancer sera and progressively increased with increasing clinical stage." (PMID 22363243, 2011).
thyroid cancer (4 papers, 2021 to 2025). "Key metabolic regulators such as IDH1, PGAM1, NDUFS3, and LDHB were identified among these common genes, suggesting their central role in thyroid cancer metabolism." (PMID 40861812, 2025). "HYOU1 has been reported to encourage tolerance of glucose and malignant progression in thyroid cancer cells by upregulating LDHB expression." (PMID 38291366, 2024). "Thirdly, bioinformatics analysis using Starbase data demonstrated significant negative correlation between LDHB mRNA and miR‐375‐3p expression in many kinds of cancer, including thyroid cancer." (PMID 33792181, 2021).
viral infection (4 papers, 2021 to 2025). "Altogether these results demonstrate that LDHB expression in suppressed pDCs restores their function, and that during in vivo viral infection, the presence of pDCs that resist functional loss was accompanied with increased IFN-I dependent colitis." (PMID 39920132, 2025). "Intriguingly, we observed no significant increase in pathology in the small intestine or liver of these animals, suggesting that some tissues may be more susceptible to pathology caused by LDHB-expressing pDCs during viral infection." (PMID 39920132, 2025). "This suggests that LDHB expression and pDC inhibition manage a trade-off between supporting pDC function and opposing host-pathology during viral infection." (PMID 39920132, 2025). "Meanwhile, IFI6, IFITM2, ISG15, and LDHB were highly expressed in memory CD4+T cells, which were crucial for cell hypermetabolism and defense against virus infection." (PMID 35095832, 2021).
bladder cancer (3 papers, 2011 to 2023). "Fb, LDHB, Apo-A1 and CLU showed increasing trend in urine samples of patients with bladder cancer, compared with healthy control, while Hp expression didn't change significantly." (PMID 21496341, 2011). "Furthermore, to validate the biological functions of histone lactylation in bladder cancer, we eliminated endogenous LDHA and LDHB to reduce global lactylation and H3K18 lactylation levels and replenished sodium lactate for rescue experiments." (PMID 37684641, 2023). "We observed increased expression of five proteins, including fibrinogen (Fb), lactate dehydrogenase B (LDHB), apolipoprotein-A1 (Apo-A1), clusterin (CLU) and haptoglobin (Hp), which were increased in urine samples of patients with low malignant or aggressive bladder cancer." (PMID 21496341, 2011).
cholangiocarcinoma (3 papers, 2019 to 2021). A carcinoma that arises from the intrahepatic biliary tree (intrahepatic cholangiocarcinoma) or from the junction, or adjacent to the junction, of the right and left hepatic ducts (hilar cholangiocarcinoma). "Here we showed that LDHA and LDHB both exhibited hydrogen peroxide-producing activity, which was significantly enhanced by the superoxide generated from the isolated mitochondria from HeLa cells and patients’ cholangiocarcinoma specimen." (PMID 34176927, 2021).
liver cancer (3 papers, 2012 to 2024). An epithelial or non-epithelial malignant neoplasm that arises from the liver. "Moreover, we validated the expression levels of LDHB mRNA and protein in four different liver cancer cell lines by qRT-PCR and western blotting, respectively." (PMID 38739169, 2024). "On the other hand, LDHB was down-regulated in several types of tumors, including liver cancer." (PMID 38739169, 2024). "Indeed, suppression of LDHB could enhance liver cancer cell glycolysis and invasiveness via lactate release in vitro." (PMID 38739169, 2024).
metastatic melanoma (3 papers, 2009 to 2020). A melanoma that has spread from its primary site to another anatomic site. "The mean increase in LDHB expression was even higher, and, in particular between nevi and metastatic melanomas (approximately 10-fold)." (PMID 23043612, 2012). "LDHB was over-expressed in archival metastatic melanoma and nasopharyngeal carcinoma." (PMID 33053689, 2020).
neuroblastoma (3 papers, 2022). Neuroblastoma (NB) is the most common solid, extracranial childhood tumor. "While complementary roles of LDHA and LDHB in brain tumor development have been reported in a neuroblastoma model, double LDHA/B KO in GB stem‐like cells induced a substantial decrease in tumor development via lactate production and consumption impairment." (PMID 36278433, 2022).
oral squamous cell carcinoma (3 papers, 2015 to 2025). "It was shown before that silencing of LDHB renders oral squamous cell carcinoma cells more sensitive to Paclitaxel, which disrupts mitotic spindle disassembly and thus blocks cell division." (PMID 40790017, 2025). "A previous study reported that cisplatin treatment reduces LDHA expression in human oral squamous cell carcinoma cell lines, suggesting that changes in LDHA levels may add complexity to the interpretation of LDHB-mediated effects in this context." (PMID 40790017, 2025).
ovarian carcinoma (3 papers, 2016 to 2024). A malignant neoplasm originating from the surface ovarian epithelium. "The results revealed that the expression of critical glycolytic enzymes (such as Glu, T4MCT4 and LdhB) in ITGB2 overexpressing ovarian cancer cells was obviously upregulated compared with that in the NC group, while the knockdown of PI3K and AKT reversed this change." (PMID 38345576, 2024).
papillary thyroid cancer (3 papers, 2013 to 2024). "ELISA assays and WB analysis confirmed the increase of LDHB, Moesin, and ANXA1 in pre-surgical FNA of thyroid papillary cancer." (PMID 24023790, 2013).
squamous cell carcinoma (3 papers, 2022). A carcinoma arising from squamous epithelial cells. "Squamous cell carcinoma patients with positive LDHB expression (which correlated with serum LDH) had higher recurrence-free survival in comparison to patients without LDHB expression." (PMID 36551514, 2022). "In particular, LDHB may serve as a specific prognostic predictor in the squamous cell carcinomas subtype of NSCLC." (PMID 36532721, 2022). "Another study examined the correlation between LDHB expression and the serum levels of LDH and showed their prognostic significance in squamous cell carcinoma." (PMID 36551514, 2022). "However, serum LDHB-positive NSCLC patients presented higher recurrence-free survival rates than did LDHB-negative cases, particularly those of the squamous cell carcinoma subtype." (PMID 36532721, 2022).
uterine cancer (3 papers, 2018 to 2022). Primary or metastatic malignant neoplasm involving the uterine corpus and/or the cervix. "In uterine cancer patients, high expression of MCT1, together with LDHB, predicts poor survival because LDHB actively controls lysosomal activity in oxidative cancer cells." (PMID 36407005, 2022). "Of note, LDHB has not yet been explored in the GB context, unlike in uterine cancer where LDHB activity modulates autophagy." (PMID 36278433, 2022).
acute myeloid leukaemia (2 papers, 2020 to 2025). "In acute myeloid leukemia cells, FTO promotes the expression of phosphofructokinase platelet and lactate dehydrogenase B expression, two key factors in aerobic glycolysis." (PMID 40532011, 2025).
alcoholic liver diseases (2 papers, 2022 to 2025). A disorder caused by damage to the liver parenchyma due to alcohol consumption. "In alcoholic liver disease, LDH family enzymes are also upregulated under chronic inflammation and hypoxia; notably, LDHB knockdown alleviated ethanol-induced liver injury, linking lactate metabolism to alcohol-related HCC." (PMID 40717080, 2025). "In addition, ginseng Huang jiu could improve alcoholic liver disease by regulating the GSTP1, HRAS, AKR1B1, GSTA1, Androgen receptor (AR), GSR, and LDHB genes through bioinformatics analysis." (PMID 36034901, 2022).
Alzheimer disease (2 papers, 2021 to 2023). A progressive, neurodegenerative disease characterized by loss of function and death of nerve cells in several areas of the brain leading to loss of cognitive function such as memory and language. "LDHB was also significantly down-regulated in excitatory neurons, astrocytes and oligodendrocytes of Alzheimer's disease patients with early pathology." (PMID 33977265, 2021).
Cirrhosis (2 papers, 2009 to 2023). A chronic disorder of the liver in which liver tissue becomes scarred and is partially replaced by regenerative nodules and fibrotic tissue resulting in loss of liver function. "In this study, the gene expression level of lactate dehydrogenase B increased from the cirrhosis phase to the metastasis phase." (PMID 19638242, 2009).
Insulin resistance (2 papers, 2024 to 2025). Increased resistance towards insulin, that is, diminished effectiveness of insulin in reducing blood glucose levels. "Elevated LDHB levels may reflect enhanced glycolytic activity, potentially linked to insulin resistance." (PMID 39702179, 2024).
invasive ductal carcinoma (2 papers, 2016 to 2020). "We showed significantly higher LDHA and lower LDHB protein expression in malignant tumor tissue than benign tumor tissue, which is a typical signature of luminal type A invasive ductal carcinoma." (PMID 33353120, 2020).
ischemia (2 papers, 2020 to 2023). A hypoperfusion of the BLOOD through an organ or tissue caused by a PATHOLOGIC CONSTRICTION or obstruction of its BLOOD VESSELS, or an absence of BLOOD CIRCULATION. "It is considered that DRP-2 and LDHB are specific targets of oxidative stress by ischemia insult and high carbonylation levels of DRP-2 may play an important role in modulating ischemic neuronal death." (PMID 33041514, 2020). "Lactate from the ANLS involving lactate metabolism-related factors, lactate dehydrogenase A (LDHA), LDHB, and monocarboxylate transporter 4 (MCT4) increases the energy supplied to neurons from astrocytes in protecting against ischemia-induced neuronal death." (PMID 36830049, 2023). "On the contrary, carbonylation level of dihydropyrimidinase related protein 2 (DRP-2) and l-lactate dehydrogenase B chain (LDHB) were slightly increased in CA1 but remarkably increased in DG after ischemia." (PMID 33041514, 2020).
maxillary sinus squamous cell carcinoma (2 papers, 2012 to 2025). A squamous cell carcinoma that arises from the mucosal epithelial surface of the maxillary sinus. "In a previous study, the expression of lactate dehydrogenase B (LDHB) was directly regulated by miR-375, which suppressed the proliferation and invasion of maxillary sinus squamous cell carcinoma." (PMID 39930542, 2025).
metastatic tumors (2 papers, 2023 to 2025). "We also find a negative partial correlation between normalized levels of LDHA and LDHB with lactate in primary tumors and a positive partial correlation between them in metastatic tumors." (PMID 36894939, 2023). "We find that in metastatic tumors, both LDHA and LDHB produce lactate, while in primary tumors, both LDHA and LDHB use lactate as a substrate to produce pyruvate." (PMID 36894939, 2023). "This indicates that LDHA and LDHB may operate in their non-preferential direction, to control the production of lactate in metastatic tumors and its breakdown in primary tumors." (PMID 36894939, 2023). "Four other glycolytic genes, ENO1, PGM1, LDHB, and PGK19, were upregulated in metastatic tumors compared to non-metastatic tumors." (PMID 40821334, 2025).
myocardial ischemia (2 papers, 2022 to 2024). A disorder of cardiac function caused by insufficient blood flow to the muscle tissue of the heart. "Lactate dehydrogenase B (LDH-B), a subunit of the lactate dehydrogenase enzyme, plays a central role in cardiac energy metabolism by utilizing lactic acid, a by-product of anaerobic glycolysis, as an energy substrate during myocardial ischemia." (PMID 39772209, 2024). "Proteins, such as LDHB, PGAM2, GOT1, PKM2 or AK1, whose expressions are decreased in hCOX-2 Tg animals, have been identified as potential biomarkers during myocardial ischemia." (PMID 36362254, 2022).
Obesity (2 papers, 2020). Accumulation of substantial excess body fat. "Interactome network analysis of the lower expressed genes in FTO obesity-risk genotype suggests that under normal conditions, DECR1 (dienoyl-CoA reductase), LIPE, LDHB, SOD2, ATP5B, and J are central elements in maintaining connectivity." (PMID 32316277, 2020). "Cross-examination of benign and malignant tumor tissue biopsies revealed a significant shift in LDH isozyme expression towards the “muscle-type” LDH with corresponding changes in protein expression of LDHA (increased) and LDHB (decreased) in malignant tumor tissue, regardless of obesity." (PMID 33353120, 2020).
psychosis (2 papers, 2019 to 2023). "Increased LDHB expression has been associated with the first onset of psychosis in antipsychotic-naïve schizophrenia patients." (PMID 30655502, 2019).